GPR55 (G protein-coupled receptor 55)
Diseases named in the same sentence as GPR55 in open-access papers (continued):
Sharing a sentence is not in itself a finding about the gene and the disease.
cancer (continued). "Along with the classical CB1 and CB2 receptors, other families of GPCRs including GPR119, GPR35, and GPR55 are emerging as novel targets in the treatment of many diseases like cancers and gastrointestinal diseases." (PMID 37834122, 2023). "Further, GPR55-mediated overstimulation of NK cells has been reported cancer, which is highly crucial in cancer immunosurveillance." (PMID 37688769, 2023). "In cancer, GPR55 has been described to show accelerating and decelerating effects in tumor progression resulting from distinct intracellular signaling pathways." (PMID 37998380, 2023). "Other effects of CBD include inhibition of GPR55, known to be elevated in several cancers such as aggressive triple negative breast cancer, where elevated levels are associated with higher chance of developing metastases." (PMID 35205633, 2022). "GPR55 is related directly or indirectly with changes that promote malignant growth including uncontrolled cancer cell proliferation, angiogenesis, cancer cell adhesion, cancer cell migration, and metastasis." (PMID 35205633, 2022). "Stimulation of GPR55 promotes cancer cell proliferation and tumor growth in vitro and in vivo via activation of ERK pathway." (PMID 36291926, 2022). "The underlying mechanisms for the SPL‐mediated cancer progression are the activation of p38 and mitochondrial function through the LPI, LPG‐GPR55 axis and the suppression of autophagy in a GPR55‐independent manner." (PMID 36125914, 2022). "Genetically distinct CB3, also known as GPR55, is also overexpressed in many cancers, including GBM." (PMID 36497400, 2022). "In particular, S1P5 strongly and specifically interacts with GPR55, and the activation of each receptor led to increased cell proliferation, ERK phosphorylation and cancer-associated gene expression." (PMID 36232401, 2022). "There are several reports indicating that the signaling pathways activated by LPI via its receptor GPR55 play crucial roles in different cancers." (PMID 36125914, 2022). "Recently, we have shown that a reduction of GPR55 activation by LPI, caused by the inhibition of the LPI ABCC3 transporter, was able to decrease cancer cell growth and increase sensitivity to chemotherapy in prostate cancer." (PMID 35204820, 2022). "Other research has found that CB2 receptors and GPR55, both of which are elevated in most tumours and control cancer cell fate, form heteromers in cancer cells and that targeting these heteromers modulates cancer cell signalling." (PMID 35205633, 2022). "GPR55 has been shown to activate the Rho family of GTPases and has been indicated to have roles in cell migration outside of cancer, including in osteoclasts." (PMID 34313032, 2022). "CBD was shown to significantly decrease adhesion to endothelial cells and migration of HCT116 cells (metastatic colon cancer cell line), an inhibitory effect that was prevented by GPR55 siRNA knock down in cancer cells." (PMID 35205633, 2022). "In fact, GPR55 has recently emerged as a therapeutic target for several diseases, including cancer and neurodegenerative and metabolic disorders." (PMID 35890067, 2022). "Our previous work has established the approximate equipotency of (R,R′)-MNF and the GPR55 antagonist CID16020046 at lowering chemoresistance in a number of cancer cell types including PANC-1 cells." (PMID 35256673, 2022). "In the tumor setting, a large quantity of LPI is usually present and activates GPR55 with a consequent increase of cancer cell proliferation." (PMID 33435517, 2021). "We demonstrated that this molecule indeed activates GPR55 in various cancer cell lines and induces cell death via this receptor." (PMID 33435517, 2021). "Anandamide, a bioactive lipid endocannabinoid, acts as a biased agonist of GPR55 and induces cancer cell death, but is unstable and psychoactive." (PMID 33435517, 2021).
cancer (continued). "In this study, among the endocannabinoids and similar compounds we identified NADA as the most active GPR55 activator, being able to induce cancer cell death via this receptor activation." (PMID 33435517, 2021). "For what concerns GPR55, it was found in several cancer types, such as glioma, melanoma, breast, prostate, ovarian and pancreatic cancer." (PMID 34943903, 2021). "Further support for a feed-forward pathway in carcinogenesis comes from studies of other types of cancer cells where GPR55 is also upregulated." (PMID 34324032, 2021). "The capacity to synthesize LPI was enhanced in various types of tumors, indicating that cancer cells can hijack the motility-related activity of GPR55 to increase aggressiveness." (PMID 34948125, 2021). "This analysis supports the concept that cancer-related GPR55 overactivation occurs predominantly due to the increased generation of endogenous agonist, and upregulation of GPR55 is secondary." (PMID 34948125, 2021). "In view of the pro-proliferative activity of GPR55 in cancer, its inhibitors are viewed as potential antitumor agents." (PMID 33435517, 2021). "Although several studies have highlighted the role of GPR55 in various types of cancer, there have been no studies (to our knowledge) on the expression of GPR55 and its potential role in EC." (PMID 34324032, 2021). "LPI binding to GPR55 drives the proliferation of cancer cells, often in an autocrine fashion, via the activation of the G protein-RhoA/Rho kinase (Rho/ROCK)-PLC signalling axis, resulting in intracellular Ca2+ release from the endoplasmic reticulum (ER)." (PMID 32340151, 2020). "It is recognised that THC binds to CB1 and CB2 while CBD acts as an antagonist of GPR55, which cause inhibition of ERK- and AKT-dependent pathways to promote apoptosis and to suppress proliferation of cancer cells." (PMID 33126623, 2020). "Among others, the CB2 receptor- GPR55 heteromers were found to be involved in cancer cell fate of different cancers, such as breast cancer, where its targeting reduces tumor growth." (PMID 31979368, 2020). "This is well in line with previous results we obtained in the azoxymethane + DSS cancer model, in which genetic knockout of GPR55 led to a substantially altered T- and myeloid-derived suppressor cell (MDSC) profile when compared to wild-type mice." (PMID 30196316, 2019). "GPR55 is widely expressed and has been proposed as a potential therapeutic target for a range of diseases, including cancer, metabolic disorders, pain, and inflammation." (PMID 31675498, 2019). "Regarding a possible role in cancer regression by cannabinoid action, GPR55 emerged as a promising target." (PMID 31143113, 2019). "Considering that GPR55 promotes cancer cell proliferation, peptide binders of GPR55 have been prepared and studied to inhibit the proliferation of EHEB and DeFew cells, two GPR55-positive B-lymphoblastoid cell lines." (PMID 31214034, 2019). "In Open Target, GPR55 and the precursors beta-microseminoprotein and clusterin-like protein 1 all have a strong link to neoplasm, supporting a potential link to cancer." (PMID 31675498, 2019). "The modulation of these important biological determinants indicates that GPR55 is a possible pharmacological target in a number of diseases where these pathways are deregulated, such as cancer." (PMID 30627539, 2018). "The available data demonstrate that cannabinoids directly activate these four GPCRs in the CNS, and they also activate GPR55 in cancer." (PMID 29066974, 2017). "The evidence that LPI can be released from cancer cells suggests that GPR55 signaling can affect the tumor microenvironment and promote bone metastases." (PMID 28029647, 2017). "Despite the numerous studies illuminating the physiological functions of GPR55 in the CNS (section GPR55 in CNS), limited information is available about the role of this receptor in cancer." (PMID 29066974, 2017).
cancer (continued). "As the GPR55 gene is highly expressed in cancer B cells, we performed this analysis in EHEB and DeFew cells, two B-lymphoblastoid cell lines." (PMID 28029647, 2017). "Together, these findings support that GPR55 activation elicits pro-invasive responses in cancer cells by binding to Gq/11 heterotrimeric G proteins and activating RhoA." (PMID 27340777, 2016). "Increasing evidence supports that GPR55 is an important component of the molecular circuitry that controls cancer cell behavior." (PMID 27340777, 2016). "First, we studied the role of GPR55 in cancer cell invasion, a pivotal event involved in the generation of metastases." (PMID 27340777, 2016). "The orphan G protein-coupled receptor GPR55 has been directly or indirectly related to basic alterations that drive malignant growth: uncontrolled cancer cell proliferation, sustained angiogenesis, and cancer cell adhesion and migration." (PMID 27340777, 2016). "Based upon knowledge of such links between LPI and cancer, numerous studies have explored the link between GPR55 and cancer." (PMID 25926795, 2015). "GPR55 is a G protein-coupled receptor with lipid-sensing properties and its up-regulation contributes to the aggressive behavior of various cancer types." (PMID 25889562, 2015). "Recent studies found prominent roles for GPR55 in neuropathic/inflammatory pain, cancer and bone physiology." (PMID 23565223, 2013). "Studies with GPR55 loss-of-function mutant mice or cultured cells suggested a role for GPR55 in pain, bone physiology, cancer, as well as glucose homeostasis." (PMID 23565223, 2013). "One of them is the slow release of CBD from the nanoemulsions, which could hinder, within the evaluated time frame, the interaction of CBD with membrane receptors such as GPR55 and TRPVs, which can modulate the viability of cancer cells." (PMID 40870993, 2025). "Importantly, we observed increased cell migration of DU145 cells treated with both lactate concentrations, which is prevented by the incubation with ML193, suggesting a potential lactate-induced GPR55 activation that enhances cancer cell motility." (PMID 40434517, 2025). "Finally, with all the in silico and in vitro data obtained regarding the expression of PINK1 and GPR55 and their potential modulation in cancer models, we decided to compare these findings with data from public databases." (PMID 40565152, 2025). "Pharmacological inhibition of GPR55 has provided promising results across various cancer models." (PMID 40434517, 2025). "Studies have shown that GPR55 plays a pro-tumorigenic role in many types of cancer." (PMID 39885986, 2024). "Investigations of GPR55-mediated cell death after treatment of different cancer cell lines with N-docosahexaenoyl dopamine (DHA-DA), considered as biased agonist of GPR55, showed increased expression and synthesis of nNOS as well as increased production of NO after DHA-DA stimulation." (PMID 38796643, 2024). "In many types of cancer that have been studied, GPR55 primarily plays a pro-tumorigenic role." (PMID 39885986, 2024). "Aiming to test whether the GPR55-mediated migration of MCs could be involved in their recruitment to malignant tumors, we evaluated the chemotaxis of BMMCs towards conditioned media from distinct murine and human cancer cell lines." (PMID 37047288, 2023). "The overexpression of GPR55 promoted cancer cell proliferation." (PMID 37185752, 2023). "This lipid adduct can be an agonist of GPR55, a G-protein coupled receptor, whose biological activities include the modulation of immune cells and insulin secretion, and also have a potential mitogen activity in cancer cells." (PMID 36552648, 2022). "Finally, GPR55 is expressed in various types of cancer, and when activated, it also promotes cancer cell proliferation." (PMID 36144803, 2022).
cancer (continued). "However, as consideration of this receptor as a member of the endocannabinoid system has a relatively recent history, the number of publications focusing on the effects of cannabinoids on GPR55‐mediated cancer cell invasion is fewer than for CB1 and CB2." (PMID 34313032, 2022). "Considering these roles together with our finding, GPR55 could be a potential target for anti‐cancer therapies and as a prognostic biomarker." (PMID 36125914, 2022). "Moreover, by over-activating the MAPK/ERK cascade, GPR55 promoted cancer cell proliferation, observed as higher Ki67 expression, in both cell cultures and xenografted mice." (PMID 36497400, 2022). "GPR55 is expressed in several peripheral organs, such as the gastrointestinal tract, pancreas, bone tissue, vascular endothelial cells and immune system, representing a novel therapeutic target for the treatment of diabetes, osteoporosis and cancer." (PMID 35890067, 2022). "Moreover, pharmacological inhibition of GPR55 enhances doxorubicin cytotoxicity in cancer cells through inactivation of MEK/ERK and PI3K/AKT pathways." (PMID 36291926, 2022). "Two other potential receptors that could represent CBRs expressed in cancer cells are GPR55 and GPR18." (PMID 35328467, 2022). "As this review focuses on the receptors of the endocannabinoid system that are implicated in cancer cell invasion, the focus will be placed on CB1, CB2, as well as GPR55 and GPR18, receptors that have been the focus of research examining the effects of cannabinoids on cancer cell invasion." (PMID 34313032, 2022). "Interestingly, N-docosahexaenoyl dopamine triggers apoptosis of cancer cells via activation of GPR55, and LPI enhances the cytotoxic effect." (PMID 36291926, 2022). "Other papers have shown an increase in cancer cell migration mediated through GPR55." (PMID 34313032, 2022). "In regard to the mechanisms of involvement of this SPL‐mediated pathway in cancer progression, we propose that both a GPR55‐dependent pathway and GPR55‐independent pathway may be involved." (PMID 36125914, 2022). "CBD can inhibit the expression of GPR55, which is related directly or indirectly with changes that promote malignant growth, including uncontrolled cancer cell proliferation, angiogenesis, cancer cell adhesion, cancer cell migration, and metastasis." (PMID 35893789, 2022). "Except for cancer cells, GPR55 is expressed by macrophages, neutrophils, and lymphocytes." (PMID 34503163, 2021). "We hypothesized that other endocannabinoids and structurally similar compounds, which are more hydrolytically stable, could also induce cancer cell death via GPR55 activation." (PMID 33435517, 2021). "However, in some cancers, e.g., cholangiocarcinoma, GPR55 activation has an antiproliferative effect, and thus the clinical use of the antagonists of this receptor is controversial." (PMID 33435517, 2021). "Thus, several GPR55-selective antagonists were synthesized and demonstrated to inhibit cancer growth and reduce cancer chemoresistance." (PMID 33435517, 2021). "The accumulation of the lipid agonist LPI occurs in cancer cells, indicating that tumors may hijack the natural motility-related function of GPR55 to increase invasiveness." (PMID 34948125, 2021). "GPR55 is overexpressed in several tumour cells, with GPR55 expression shown to correlate with tumour aggressiveness and GPR55 activation to promote cancer-cell proliferation both in cell culture and in xenografts in mice." (PMID 33902596, 2021). "It was postulated that the LPI/GPR55 axis plays a crucial role in tumor progression, and that blocking this pathway might be a promising strategy to inhibit cancer-promoting mechanisms, especially tumor cell proliferation." (PMID 33802282, 2021). "CID16020046 is a selective GPR55 antagonist recently used in the anti-cancer research." (PMID 34943903, 2021). "GPR55 is also reportedly a regulator of the migration of several types of cancer cells." (PMID 32121640, 2020).
cancer (continued). "Several reports indicate that GPR55 plays a crucial role in cancer progression." (PMID 32718079, 2020). "Furthermore, a crosstalk between CB2 receptors and GPR55 was identified as a determinant of cancer progression." (PMID 31143113, 2019). "As cannabinoids modulate the activity of GPR55, its anti-cancer effects have been analyzed as well." (PMID 31024307, 2019). "Increased expression of GPR55 and severity and malignancy of the disease has been reported in different cancer types, such as the human pancreatic ductal adenocarcinoma, the squamous cell carcinomas human astrocytoma, the melanoma, the B lymphoblastoma, and the hepatocellular carcinoma as well." (PMID 30627539, 2018). "Increased expression levels of GPR55 can confer a proliferative advantage to cancer cells in cell culture and in tumor-xenograft mice, as a consequence of hyper-activation of the extracellular signal-regulated kinase cascade, one of the master regulators of cell proliferation." (PMID 28029647, 2017). "Increasing evidence has also delineated the role of GPR55 in cancer development, as it is overexpressed in several tumor cells, including glioblastoma, astrocytoma, breast carcinoma, melanoma, ovarian carcinoma, B-cell multiple myeloma, and B-lymphoblastoid cells." (PMID 28029647, 2017). "GPR55 is expressed in different cancer cell types raising the possibility that it may be a target for cancer chemotherapeutic agent development." (PMID 29066974, 2017). "In addition, diverse range of human cancer cell lines are also expressing GPR55 including ovary, prostate, breast, skin, as well as cervix, liver, blood and pancreas." (PMID 26784247, 2016). "GPR55 has been shown to activate Rho GTPases in non-cancer contexts." (PMID 27340777, 2016). "Indirect links between GPR55 and metastasis have been previously suggested in other cancer types." (PMID 27340777, 2016). "GPR55 activation also enhanced cancer cell mitogenic activity and metastases." (PMID 23565223, 2013). "For example, GPR55 deletion ablates hyperalgesia following partial nerve ligation and injection of complete Freund’s adjuvant and activation of GPR55 promotes cancer cell proliferation and GPR55 expression levels positively correlate with tumor aggressiveness across multiple tumor types." (PMID 23565223, 2013). "It was also reported that GPR55 promoted cancer cell proliferation by ERK." (PMID 23527081, 2013). "Thus, GPR55 is indispensable in the SPL pathway in cancer cells to induce and support continuous growth of the cells through binding LPI or LPG and furthermore, for activation of the p38 signal cascade, considering the established roles of p38 in the pathogenesis of cancer." (PMID 36125914, 2022). "In addition, in some cancers AA-EA and other cannabinoids are pro-proliferative, which could be due to difference in the GPR55 downstream signaling, induced by AA-EA and LPI." (PMID 33435517, 2021). "In this context, GPR55 might represent an optimal target for cancer therapy." (PMID 28029647, 2017). "In addition to its possible role as a precursor of LysoPA, LysoPI might possess direct roles in the pathogenesis of cancers, because GPR55 has been identified as a specific GPCR for LysoPI and LysoPG is also reportedly involved in inflammation." (PMID 28143894, 2017). "In addition, the LPI/GPR55 system is also involved in inflammation and cancer." (PMID 26784247, 2016). "Clearly, GPR55 is an exciting, novel, and underexplored receptor around which it may be possible to develop therapies for neuropathic pain, osteoporosis, cancer, and obesity." (PMID 23565223, 2013). "GPR55 is an orphan G protein-coupled receptor (GPCR) and represents a promising drug target for cancer, inflammation, and metabolic diseases." (PMID 40000629, 2025). "Regarding GPR55, it has been increasingly recognized as a potential oncogene in the carcinogenic development of GBM, as well as in other types of cancer." (PMID 40565152, 2025).